ENSG00000293663 (novel protein similar to embryonic testis differentiation homolog A)
Gene: Protein-coding gene on chromosome X (135,391,849 to 135,392,207, reverse strand). Ensembl gene ENSG00000293663.
Homologues: Orthologues: mouse 1600025M17Rik (39% identical). Paralogues in human: SMIM10L2B-AS1 (80% identical).